SIRT1 (sirtuin 1)
Diseases named in the same sentence as SIRT1 in open-access papers (continued):
Sharing a sentence is not in itself a finding about the gene and the disease.
ischemic stroke (continued). "However, it remains unclear how Sirt1 regulates the interaction between Notch signaling and VEGF to promote angiogenesis in ischemic stroke." (PMID 37622049, 2023). "Surprisingly, the Sirt1 inhibitor EX-527 was shown to be as effective as necrostatin-1 in suppressing the elevation of RIP3 and MLKL, leading to reduced infarct volumes, which indicated that suppression of Sirt1 provided the neuroprotection against ischemic stroke by inhibiting necroptosis." (PMID 37622049, 2023). "Thus, SIRT-1, ERK, and JNK might involve in regulating apoptosis and autophagy after EA treatment in the acute stage of ischaemic stroke." (PMID 33603645, 2021). "In summary, we prove that USP29 upregulation during cerebral I/R injury is essential for oxidative damage and neuronal apoptosis of the brain through regulating SIRT1 and that targeting USP29 may be helpful for designing effective therapeutic strategies for ischemic stroke." (PMID 34824671, 2021). "In addition to SRT1720, molecules structurally unrelated to resveratrol, such as SRT2104, SRT2379, and SRT3657, have been developed to stimulate the activity of sirtuins, but similar to SRT1720 these SIRT1 activators have not been shown to have a neuroprotective effect in models of ischemic stroke." (PMID 34680562, 2021). "Our work is devoted to studying the role of non-mitochondrial sirtuins SIRT1 and SIRT2 in brain cells after ischemic stroke." (PMID 35574497, 2022). "In the present review we focus on the role of non-mitochondrial SIRT1, SIRT2, and SIRT6 in the brain damage and recovery after ischemic stroke." (PMID 34680562, 2021). "Moreover, it was shown that SIRT1, SIRT2, and SIRT6 were not involved in ischemic stroke-induced penumbra cell apoptosis." (PMID 35625059, 2022).
coronary artery disease (60 papers, 2013 to 2026). "Previous studies have associated SIRT1 gene polymorphisms with coronary artery calcification, abnormalities in cholesterol metabolism, and early-onset coronary artery disease." (PMID 34563044, 2021). "Polymorphisms in SIRT1 gene have been associated with coronary artery calcification, abnormalities in cholesterol metabolism, and early-onset coronary artery disease." (PMID 34563044, 2021). "The results showed that the AMPK phosphorylation level of rats with chronic heart failure caused by ischemic heart disease after the intervention of Linggui Zhugan Decoction increased, while the protein and mRNA levels of SIRT1 and PGC-1α were significantly increased." (PMID 37089931, 2023). "We observed a decline in SIRT1, SIRT3, and SIRT6 levels, broadly consistent with a ~50% reduction in SIRT1 reported in ischemic heart disease cohorts and a ~35% decline in SIRT3 under pressure-overload conditions." (PMID 41154755, 2025). "SIRT1 expression in PBMCs isolated from patients with stable coronary artery disease (CAD) and acute coronary syndromes is reduced as compared to subjects without angiographically demonstrable CAD." (PMID 40507709, 2025). "It has been demonstrated that patients with coronary artery disease show lower SIRT1 mRNA expression and higher IL-6 expression in blood monocytes versus healthy controls." (PMID 41228388, 2025). "Inhibition of microRNA-323-3p inhibits vascular endothelial cell apoptosis by promoting sirtuin-1 expression in coronary artery disease." (PMID 39680523, 2024). "Diosgenin prevents coronary heart disease by reducing oxidative stress and inflammation levels through Sirt1/Nrf2 and p38 MAPK pathways." (PMID 39680523, 2024). "Our cardiac findings align with a study that reported reduced cardiac fibrosis after systemic miR-181c-5p inhibition in a mouse model with coronary artery disease through SIRT1-targeting." (PMID 38725830, 2024). "Clinical studies have shown that resveratrol, a SIRT1 activator, has a benign effect on diastolic function in subjects with coronary heart disease." (PMID 36840496, 2023). "The deactylation of PGC-1α by SIRT1 enhances its activity, promotes mitochondrial biogenesis, and plays a protective role in neuronal injuries and in ischemic heart disease." (PMID 38304233, 2023). "Downregulation of miR-199a has been noted in acute heart failure and leads to an increase in SIRT1 expression in postoperative atrial fibrillation and coronary heart disease." (PMID 36071532, 2022). "Sirtuin1 (SIRT1) was lowly expressed in atherosclerotic plaque tissues in coronary heart disease patients and in ox-LDL-induced hVSMCs." (PMID 35038972, 2022). "Liquiritin plays a protective role in coronary heart disease by regulating the proliferation and migration of hVSMCs by increasing SIRT1 expression, which would provide new ideas for coronary heart disease treatment." (PMID 35038972, 2022). "To study the effect of liquiritin on SIRT1 expression in coronary heart disease, we measured the mRNA and protein expression levels of SIRT1 in hVSMCs and patient-related tissues." (PMID 35038972, 2022). "Accordingly, the expression of SIRT1 in peripheral blood mononuclear cells (PBMCs) of patients with coronary artery disease was significantly correlated with inflammatory cytokines levels." (PMID 34656137, 2021). "On the other hand, the fact that SIRT1 functions in ischemic heart disease by regulating its downstream NF-κB/I-κB pathway has been reported." (PMID 33574759, 2020). "A recent study showed that the combination of vitamin E (400 IU/day) and omega-3 fatty acid (4 g/day) for 2 months upregulated sirtuin-1 gene expression of the peripheral blood mononuclear cells in patients with coronary artery disease." (PMID 30186176, 2018). "The study on signaling pathway of ischemic heart disease showed that the SIRT1-FOXO pathway is a major signaling pathway for inhibition of myocardial apoptosis." (PMID 25114706, 2014).
coronary artery disease (continued). "In patients with coronary artery disease, SIRT1 gene expression levels are significantly decreased." (PMID 36747995, 2023). "In addition, coronary artery disease can lead to the activation of the SIRT1/FoxO1 signaling pathway and activation of the apoptotic signaling pathway, and safflower can reverse this result." (PMID 35607519, 2022). "SIRT1 activators is tested as the treatment of coronary artery disease." (PMID 35038972, 2022). "EX 527 reversed the effects of liquiritin on cell proliferation, migration, and apoptosis in ox-LDL-induced hVSMCs In conclusion, liquiritin plays a protective role in coronary heart disease by regulating the proliferation and migration of hVSMCs by increasing SIRT1 expression." (PMID 35038972, 2022). "Overall, liquiritin inhibited the effects of ox-LDL on hVSMCs by increasing SIRT1 expression, thus may play a protective role in coronary heart disease." (PMID 35038972, 2022). "SIRT1 can inhibit oxidative stress and inflammation in patients with coronary artery disease." (PMID 35224092, 2022). "In addition, the plasma circ-Sirt1 level was significantly decreased in patients with coronary artery disease." (PMID 30820544, 2019). "Overall, these findings indicate that p21 deacetylation by Sirt1 may be a novel, effective strategy for inducing endogenous cardiac regeneration and protecting the heart from ischemic heart disease." (PMID 31881009, 2019). "The mechanism of this drug action might be through the impact of SIRT1-mediated signal transduction pathway on cardiomyocytes of ischemic heart disease, which provides us with a promising insight for the intervention of TCM on IHD." (PMID 25114706, 2014). "However, some studies involving patients with coronary artery disease have reported downregulation of SIRT1, implying that statins may normalize elevated baseline SIRT1 expression." (PMID 41009597, 2025). "Therefore, the dynamic network of SIRT1/SIRT3 acts as a mediator that regulates adaptive metabolic response to improve the tolerance of aged hearts to ischemic insults, which will facilitate investigation into the role of SIRT1/SIRT3 in age‐related ischemic heart disease." (PMID 37537789, 2023). "Similarly, in the rat myocardial infarction, Danqi tablets (DQT) upregulates the production of ATP in the myocardial cells of rats with ischemic heart disease through the AMPK/SIRT1-PGC-1α pathway, and inhibit the infiltration of inflammatory cells in the marginal area of MI to protect myocardium." (PMID 33574759, 2020). "We investigated two A>G SIRT1 SNPs, rs1467568 and rs7895833, in young South African (SA) Indians with coronary artery disease (CAD) and compared them to Indian and black controls." (PMID 27841908, 2016). "Some studies observed that silent information regulator 1 (SIRT1) and SIRT1-related microRNA-34a were expressed in endothelial progenitor cells obtained from patients with coronary artery disease, and microRNA-34a level was higher than that in non-coronary artery disease subjects." (PMID 24098525, 2013). "SIRT1 facilitates mitochondrial biogenesis, increases PGC-1α activity, and protects against ischemic heart disease and brain damage by deacetylating them." (PMID 41567643, 2025).
coronary artery disease (continued). "Thus, this study was designed to explore whether liquiritin can regulate the proliferation and migration of hVSMCs by regulating SIRT1 expression to impact the development of coronary heart disease, which would provide new targets for coronary heart disease treatment." (PMID 35038972, 2022). "We advocate studying the role of SIRT1 and SIRT3 in ischemic heart disease populations to address future clinical usages and therapeutic options." (PMID 34216536, 2021). "In patients with coronary artery disease, whole blood GDF11 and SIRT1 expression levels were strongly correlated." (PMID 34262905, 2021). "To investigate the critical role of SIRT1 and SIRT3 in aged‐related ischemic heart disease, we first evaluated the protein expression level of SIRT1 and SIRT3 in the young (4–6 months) and aged (24–26 months) male C57BL/6J mice left ventricle." (PMID 34216536, 2021). "Furthermore, in patients with coronary artery disease (CAD) receiving crocin (30 mg/day), SIRT1 gene expression increased significantly in peripheral blood mononuclear cells if compared to placebo-treated ones." (PMID 40806702, 2025). "A strong negative correlation of Sirt1 and the Bax/Bcl-2 ratio of gene expression was also observed in patients with coronary artery disease." (PMID 33250679, 2020). "We investigated whether long-term consumption of two healthy diets (low-fat (LF) or Mediterranean (Med)) interacts with SIRT1 genotypes to modulate aging-related processes such as leucocyte telomere length (LTL), oxidative stress (OxS) and inflammation in patients with coronary heart disease (CHD)." (PMID 36145164, 2022).
Huntington disease (59 papers, 2013 to 2025). Huntington disease (HD) is a rare neurodegenerative disorder of the central nervous system characterized by unwanted choreatic movements, behavioral and psychiatric disturbances and dementia. "FOXO3a deacetylation was another SIRT1 target implicated in promoting cell survival in Huntington’s disease models." (PMID 38672209, 2024). "Sirt1 has been linked to neurodegenerative diseases such as Huntington's disease, AD, and Parkinson's disease neuropathology." (PMID 25991666, 2015). "It has been reported that the SIRT1 agonist resveratrol protects C. elegans neurons expressing a fragment of the Huntington disease-associated protein huntingtin and mammalian neurons from mutant polyglutamine cytotoxicity in a HdhQ111 knock-in mouse model of Huntington disease." (PMID 27790141, 2016). "The upregulation of Sirt1, an enzyme known to protect motor neurons, for example, has been found to be beneficial in reducing polyglutamine disease symptoms in patients with Huntington’s Disease." (PMID 38921455, 2024). "In contrast, due to its unique inhibition mechanism, the Sirt1 inhibitor EX-527 has nanomolar potency and translational potential in Huntington’s disease but is often used in cellular studies at micromolar concentrations that also inhibit Sirt2." (PMID 38474697, 2024). "Additional explorations into Sirt1 have found that increased expression can help relieve Huntington’s Disease phenotypes." (PMID 38921455, 2024). "It is considered a therapeutic target for cancer, metabolic and neurodegenerative diseases, such as Huntington’s disease and metabolic syndrome, and a variety of small molecule Sirt1 modulators have been developed." (PMID 36361557, 2022). "On one hand, there are conditions in which SIRT1 inhibition seems to be preferable, such as cancer and Huntington’s disease." (PMID 35883477, 2022). "The SIRT1 overexpression was reported to improve cell survival in the in vitro Huntington's disease model and SIRT1 activation played a neuroprotective role in the 6-OHDA-induced AD model." (PMID 33204711, 2020). "Another neurodegenerative disease in which SIRT1 has been investigated is Huntington's disease (HD)." (PMID 33269110, 2020). "For example, selisistat (EX-527, 1), a nanomolar and selective Sirt1 inhibitor, passed phase II clinical trials as a disease-modifying therapeutic for Huntington’s disease (HD) and was acquainted by AOP Orphan Pharmaceuticals AG for phase III trials in 2017." (PMID 31598174, 2019). "While already shown to be protective against Huntington’s disease in mice, we show that increased SIRT1 expression is able to protect against mut-huntingtin toxicity in the same deacetylase-independent manner in cultured neurons." (PMID 30973934, 2019). "The SIRT1 inhibitor EX-527 was tested in a phase II clinical study in Huntington’s disease patients and was well tolerated." (PMID 31091806, 2019). "In Huntington’s disease, SIRT1 overexpression ameliorates the neurotoxic effect of the mutant protein HTT while overexpression reverses this effect." (PMID 30504847, 2018). "Numerous studies have documented that Sirt1 mediates the neuroprotective effects of resveratrol in neurodegenerative disease, such as Huntington disease." (PMID 29245987, 2017). "Sirt1 inhibition was protective in some Huntington’s disease models, and overexpression of Sirt1 induced a reference memory deficit." (PMID 28197553, 2017). "Along this theme, SIRT1 is known to mediate transcriptional activation of neuroprotective pathways preventing Huntington’s disease." (PMID 26500489, 2015). "FOXO3a deacetylation is an important SIRT1 target for cell survival in Huntington’s disease models." (PMID 38672209, 2024). "Thus, Compound 4.27 is a promising starting point to develop selective Sirt1 inhibitors that can be tested for therapeutic potential in Huntington’s disease and other aging pathologies." (PMID 38474697, 2024).
Huntington disease (continued). "SIRT1 deacetylation of mutant huntingtin prevents its degradation, thus inhibition of SIRT1 could be beneficial for patients suffering from Huntington’s Disease (HD)." (PMID 38784035, 2024). "The nuclear isoform Sirt1 deacetylates histones and transcription factors to regulate, e.g., metabolic adaptations and circadian mechanisms, and it is used as a therapeutic target for Huntington’s disease and psoriasis." (PMID 36361557, 2022). "Interestingly, REST and Sirt1 are also implicated in the pathology of Huntington’s disease, with increased expression of Sirt1 found in Huntington’s disease-affected post-mortem brains." (PMID 33813634, 2021). "Research has discovered that long-term memory formation is mediated by SIRT, and enhancing the SIRT1 expression could resist the neurodegeneration in Huntington's disease (HD) mouse brain." (PMID 32596298, 2020). "SIRT1 is protective in both in vitro and in vivo paradigms of Huntington’s disease." (PMID 30973934, 2019). "In contrast, in a transgenic mouse model overexpressing a truncated N-terminal Huntingtin protein, deletion of the Sirt1 catalytic site worsened Huntington’s disease symptoms while the overexpression of Sirt1 reduced protein aggregation improving physiological conditions." (PMID 30304806, 2018). "Thanks to these evidences, SIRT1, as well as the other sirtuins, is now considered a promising therapeutic option for neurological syndromes, such as Alzheimer, Parkinson, and Huntington's disease, and in general for the control and progression of the neuroimmunoaging." (PMID 27790141, 2016). "Furthermore, FOXO3a contributes to neuroprotection by Sirt1 in a striatal cell model of Huntington’s disease and moderate FOXO3 activation was recently shown to oppose α-synuclein accumulation and proteotoxicity." (PMID 26419537, 2015). "While a number of small molecule inhibitors of class I and II HDACs are currently in clinical trials for the treatment of malignancies of various organ origins, SIRT1 inhibition is currently only investigated in a phase I trial of patients with Huntington’s disease." (PMID 24088390, 2013). "Huntington’s disease is associated with low levels of the REST target BDNF (brain derived neurotrophic factor), and restoration of BDNF can effectively reverse the Huntington’s disease phenotype, suggesting Sirt1 and REST may exacerbate the disease by downregulation of BDNF." (PMID 33813634, 2021). "Overexpression of SIRT1 improves motor function, reduces brain atrophy, and attenuates mutant-HTT-mediated metabolic abnormalities in a mouse model of Huntington's disease." (PMID 29081884, 2017). "In animal models of AD and Huntington's disease, overexpression of Sirt-1 abrogated neuronal degeneration and nonapoptotic and apoptotic cell death and indicated the tight association of Sirt-1 to physiological processes in neurons." (PMID 33834065, 2021). "In Huntington disease (HD), Sirt1 is not able to deacetylate TORC1 that in consequence does not bind CREB, due to the presence of mutated huntingtin protein interfering with TORC1-CREB complex." (PMID 30304806, 2018). "In contrast, Sirt1 activation was protective in an ALS and other Huntington’s disease models." (PMID 28197553, 2017).